CAT (catalase)
Diseases named in the same sentence as CAT in open-access papers (continued):
Sharing a sentence is not in itself a finding about the gene and the disease.
tumor (continued). "The mitochondrial targeting moiety helps in enhancing photodynamic therapy induced cell death and the catalase encapsulated inside would decompose the tumor endogenous H2O2, thereby overcoming hypoxic environment in the tumor and enhancing the photodynamic therapy of solid tumors." (PMID 30155269, 2018). "Meanwhile, H2O2 could relieve tumor hypoxia by generating oxygen within TME triggered by CAT of those nanoparticles, which made CAT a potential treatment target in various tumors." (PMID 29850522, 2018). "After LGT administration to the tumor-bearing mice, the significantly elevated MDA and reduced GSH, GST, GPx, SOD, and CAT levels were seen compared with the tumor control group, indicating that LGT induced LPO damage and lower levels of antioxidants of tumor-bearing mice." (PMID 29950302, 2018). "Levels of lactate dehydrogenase (LDH), γ -glutamyl transferase (GGT), alkaline phosphatase (ALP), carcinoembryonic antigen (CEA) and cancer antigen 15-3(CA15-3) in serum, and also catalase (CAT) and superoxide dismutase (SOD) activities in tumor tissue were measured." (PMID 29755559, 2018). "Interestingly and in contrast to the ‘undead’ AiP model, removing intracellular ROS by misexpression of intracellular Catalase, SOD1 and SOD2 also strongly suppressed tumor growth." (PMID 28853394, 2017). "When BxPC-3 tumor cells were treated for 8 h with IFN-γ alone or in combination with PEG-catalase (to increase intracellular peroxide detoxifying capacity), the induction of HIF-1α by IFN-γ was decreased in a PEG-catalase concentration-dependent fashion." (PMID 27637085, 2016). "By contrast, in tumor cells, high levels of ROS, close to the threshold of cytotoxicity, are produced through the mitochondrial respiratory chain, and the H2O2 level is controlled by CAT." (PMID 26330167, 2015). "However, NO was tumoricidal in the presence of H2O2 because the addition of exogenous CAT, which eliminates H2O2 released into the extracellular medium, significantly decreased tumor cytotoxicity." (PMID 24802641, 2014). "In vitro, the purified MDSCs from tumor-bearing control mice were treated with various stimuli, including catalase (a ROS-quenching agent), PMA (a ROS induction agent), nor-NOHA (an arginase inhibitor), and sample." (PMID 24062783, 2013). "On the other hand, we have not observed differences in cyclin E, CDK2 and CDK4 levels between catalase-treated and non-treated cells and between non-tumor and tumor cells." (PMID 22970236, 2012). "Impairment of enzymatic activities, like GSTs, SOD and CAT, in TDA treated tumor bearing mice unveiled attenuation of enzymatic antioxidant defense mechanisms, thus aggravating oxidative stress and resulting in tumor proliferation in mice." (PMID 22319252, 2011). "where pS is the (unknown) proportion of stroma, CAS and CBS are the ASCNs of the stromal cells, and CAT and CBT are the (unknown) ASCNs in the tumor." (PMID 16322765, 2005). "In contrast, CuZn-SOD and catalase levels in the six QR clones did not have any correlation with tumour progression parameters." (PMID 10027302, 1999). "Moreover, by restoring levels of antioxidants like SOD, CAT and GSH—often depleted in GBM—this treatment may counteract oxidative stress and reduce tumour aggressiveness." (PMID 41042696, 2025). "SMNE also demonstrated efficacy in inhibiting tumor growth in mice with Ehrlich ascites carcinoma, normalizing alanine aminotransferase (ALT) and aspartate aminotransferase (AST) levels, and reducing oxidative stress markers such as catalase (CAT) and malondialdehyde (MDA)." (PMID 39762303, 2025). "The generation and consumption of H2O2 in tumor cells are maintained in a relatively stable state through a complex redox system, which involves various redox enzymes such as superoxide dismutase (SOD), catalase (CAT), peroxidase (POD), and glutathione peroxidase (GPx)." (PMID 40271909, 2025).
tumor (continued). "However, in NRNAimysRNAi gut tumours, the overexpression of catalase to buffer ROS does not rescue tumour survival, suggesting that antioxidant treatments can sometimes exacerbate rather than alleviate tumour progression." (PMID 39682725, 2024). "Furthermore, VCN-AgNPs intensified oxidative stress in tumor tissues, as evidenced by elevated levels of lipid peroxidation (LPO) and nitric oxide (NO), along with a reduction in the levels of the antioxidants investigated (GSH, GPx, GR, SOD, CAT, and TAC)." (PMID 39513869, 2024). "As demonstrated by encapsulating CAT, NanoICD/CAT-PCA effectively alleviated the immunosuppressive TME and induced robust antitumor immune responses in 4T1 tumor–bearing mice, significantly suppressing tumor recurrence and lung metastasis, and improving the survival rate of the mice." (PMID 38324678, 2024). "Consequently, our finding of significant reductions in the activities of CAT and SOD enzymes observed in the tumor tissues of mice given PSO nano-emulsions manifested the disruption of the antioxidant defense system and damage of tumor tissues by PSO-nano-emulsion." (PMID 37016062, 2023). "Moreover, PZIF-67-AT could enhance the accumulation of H2O2 in tumor cells by promoting the conversion of superoxide anions into H2O2, suppressing the catalase activity and depletion of GSH." (PMID 36593957, 2023). "While single-agent catalase was not necessarily expected to slow growth in flank tumors, it was surprising that the addition of extracellular catalase to radiation therapy did not result in additional tumor delay, as this combination has previously shown efficacy in the same tumor models." (PMID 37311396, 2023). "Besides, the DCFH-DA fluorescence shows that CAT-TCPP/FCS NPs could decompose intracellular H2O2 to generate ROS efficiently, which could relieve tumor hypoxia and enhance SDT efficacy." (PMID 36671940, 2023). "Therefore, we cannot say with certainty that extra- or intracellular catalase had no impact on hydrogen peroxide flux in the tumor, simply that any changes that did occur did not result in significant transcriptional changes or tumor growth delay." (PMID 37311396, 2023). "But these are not ideal solutions, concerns include the possibility of manganese toxicity, the lack of tumor selectivity in hyperbaric oxygen therapy, the efficiency of the treatment being constrained by hyperoxic toxicity, and the potential instability of catalase." (PMID 37120558, 2023). "In addition, oral administration of 2.5 and 5 mg/kg BW 10-HDA per day for 2 weeks in Ehrlich solid tumor mice strengthened the activity of SOD, catalase enzyme, and GSH-Px in tumor tissue, while lessening the concentrations of lipid peroxidation and nitric oxide." (PMID 35883394, 2022). "Moreover, to improve the efficacy of radiotherapy, a continuous catalase (CAT)-secreting EcN has been constructed, using CAT to catalyze the production of O2 from H2O2 in tumor cells, alleviating the hypoxic environment and increasing the sensitivity of tumors to radiotherapy." (PMID 35054790, 2022). "A higher tumor suppression ratio was achieved after intravenous injection of HA-CAT@aCe6 under 660 nm light irradiation, especially compared to the control system without CAT loading." (PMID 35119544, 2022). "Moreover, the modified peroxidase in UCNPs/MB@ZIF-8@catalase can catalyze endogenous H2O2 to produce oxygen in the tumor to overcome the two major obstacles of lack of oxygen in the tumor microenvironment and the limited depth of laser penetration during PDT." (PMID 36153522, 2022). "In addition, by performing the immunohistochemical localization of catalase, the results revealed lower or no expression of this enzyme in tumor cells." (PMID 36358570, 2022).
tumor (continued). "Indeed, we verified that the PTT can significantly elevate the catalyze-mimic (CAT) activity to relieve tumor hypoxia, as well as the peroxidase-mimic (POD) activity, which produces toxic hydroxyl radicals (•OH) that can induce the apoptosis of tumor cells." (PMID 36153526, 2022). "Catalase loaded in the zeolite could efficiently relieve tumor hypoxia by continuously decomposing endogenic H2O2 and in situ producing a large amount of O2 inside tumor, thereby promoting efficacy of O2-dependent PDT." (PMID 34138222, 2021). "In line with this conclusion, the kinetics of apoptosis induction in BSO- or sulfasalazine-pretreated tumor cells after addition of the catalase inhibitor started immediately, without showing the lag phase that is typical for control cells that had not been pretreated with BSO or sulfasalazine." (PMID 34679719, 2021). "In addition, EBF1 exhibits tumor suppressive properties in CCA cells through decrease of stemness and oxidative stress-resistant properties via suppressions of Wnt signaling pathway and antioxidants via inhibition of Oct3/4, SOD2 and CAT expression." (PMID 33854627, 2021). "Leveraging the abnormal H2O2 concentrations in tumor microenvironments, many advanced nanomedicine-based PDT strategies have been designed to relieve the hypoxic condition and elevate the therapeutic efficiency of PDT by introducing a catalase to transform endogenous H2O2 to oxygen." (PMID 33535466, 2021). "Although some antioxidants can reduce Dox-induced enhancement of ROS levels, addition of various antioxidants, including vitamin C, superoxide dismutase, N-acetylcysteine, glutathione, catalase, and probucol did not diminish the cytotoxicity of Dox in a variety of tumor cells." (PMID 33808398, 2021). "As for catalase-mimicking properties, it is well-established that INs effectively catalyze the degradation of H2O2 into water and oxygen, which could be used to relieve the hypoxia condition in the tumor microenvironment." (PMID 33134243, 2020). "Furthermore, we tested whether RNAi can prevent the tumor-like growth in the presence of overexpressed ROS scavengers, which include superoxide dismutase 1 (SOD1), SOD2 and catalase." (PMID 33199523, 2020). "A reduction in the SOD and CAT activities in the ascites fluid of control EAT-bearing mice may be the reason for tumor growth, while the treatment of mice with CA or GA controls the redox status of EAT-tumor bearing animals, thus increasing their survival." (PMID 33261130, 2020). "However, due to variable concentrations of O2− versus ⋅NO, tumor cells do not necessarily reactivate HOCl signaling after catalase inactivation." (PMID 31578342, 2019). "In another approach, application of Lactococcus lactis expressing catalase has been proven to decrease the production of reactive oxygen species (ROS) such as H2O2, reducing colonic damage, and inflammation, consequently projecting on tumor invasion and proliferation." (PMID 30949803, 2019). "This explanation has been experimentally excluded through the quantitation of NOX1 inhibition and through experiments in which tumor cell apoptosis was initiated by NO-mediated catalase inhibition, in the absence of primary 1O2 and fully dependent on secondary 1O2." (PMID 31558835, 2019). "In addition, the absence of membrane-bound catalase allows tumor cell-generated RONS to initiate an apoptotic process that takes place over typically 3–5 hours." (PMID 31578342, 2019). "On the other hand, the analysis of bystander effect-inducing and receiving processes as studied here also allow to determine discrete inactivation of a few catalase molecules on the surface of tumor cells that would not be possible to detect by the challenge with ONOO−." (PMID 31558835, 2019).
tumor (continued). "One water-soluble polysaccharide, Marsdenia tenacissima polysaccharide (MTP), can improve immune function in normal mice and inhibit tumor growth in H22 hepatic carcinoma cells in tumor-bearing mice by significantly enhancing the activities of certain substances, such as GSH-Px, SOD, and CAT." (PMID 30406035, 2018). "Catalase level was non-significant decreased in tumor extracts compared to control group (p<0,01)." (PMID 30364567, 2018). "However, SOD levels also increase with tumor progression in these and other cancers, with similar changes occurring in other antioxidants, such as cytoplasmic SOD1 and catalase." (PMID 28744456, 2017). "This low CAT activity leads to high levels of H2O2 and creates an intracellular environment favorable to DNA mutagenesis and to the activation of H2O2-dependent signaling pathways that typically trigger cell proliferation, invasion and metastatic phenotypes, consequently promoting tumor progression." (PMID 26682014, 2016). "Notably, we previously reported that catalase (an essential enzyme for the detoxification of 2H2O2 to 2H2O + O2) expression was significantly downregulated in tumor tissue relative to normal tissue, and that the NQO1 to catalase ratio is markedly increased in tumor tissue." (PMID 26462257, 2015). "One study revealed the toxin Bl-LAAO from Bothrops leucurus venom presented a cytotoxic effect on the tumor cell lines MKN-45 (stomach cancer), RKO (colorectal cancer) and LL-24 (human fibroblasts), whereas around 25% of this cytotoxicity was inhibited in the presence of catalase (100 μg)." (PMID 24940304, 2014). "Also, in the presence of catalase (150 U/mL), BatroxLAAO did not induce significant cell death on any of the tumor cell lines tested." (PMID 24940304, 2014). "However, the xenografts of MCF-10AT clone overexpressing catalase or co-treated with 20 uM Ebselen did not form palpable tumor." (PMID 23437041, 2013). "The major factors in ADS are superoxide dismutases (SOD), catalase (CAT) and gluthathione peroxidase (GPX) Antioxidant enzymes can inhibit the initiation of carcinogenesis, affect tumour progression, and their expression is reduced in many types of cancerous cells." (PMID 16868544, 2006). "In the tumor-hypoxic microenvironment, intra-nanoparticle CAT could be activated by the high concentration of H2O2 to generate O2 in situ to alleviate tumor hypoxia, improving the TME, and resulting in boosting anti-tumor chemotherapy and inhibiting tumor metastasis." (PMID 37765212, 2023). "Our data suggest these tumor models exhibit gene expression programs consistent with oxidative stress and hypoxia – however, our interventions significantly increasing extracellular and/or intracellular catalase made no detectable difference to these responses." (PMID 37311396, 2023). "Additionally, catalase (CAT) and glutathione peroxidase 3 and 4 (GPX3 and 4) in shEPOR tumors were 3.5, 5, and 3.6 times lower than those in shSCR tumors (p<0.001), implying that the proportion of shEPOR A549 cancer cells in the tumor biopsies respire less than shSCR A549 cancer cells." (PMID 36052260, 2022). "Moreover, plasmonic AgPd PB nanozyme exhibited both CAT (through Eley–Rideal mechanism) and POD-mimic activities (through Fenton-like mechanism), which were demonstrated to catalyze TME-enriched H2O2 to into O2 to relieve tumor hypoxia or into toxic •OH to induce apoptosis in vitro and in vivo." (PMID 36153526, 2022). "Therefore, tumor cells with increased numbers of aquaporins may have a better chance for selection during tumor progression, as the intrusion of sufficient H2O2 for proliferation stimulation is ensured despite the high local concentration of catalase immobilized on the cell membrane." (PMID 34679719, 2021).
tumor (continued). "Since declined levels of both GPx and catalase, reported in case of AFB1 induced HCC, are recovered back to their normal levels due to the Fisetin treatment, it may be discerned that Fisetin modulates all the three antioxidant enzymes to prevent rise in tumor supportive ROS level in the HCC liver." (PMID 26682000, 2016). "In the present study, high cAT production was specifically and primarily detected in blood of most malignant tumor types, but not in blood of benign tumors or non-tumor diseases, suggesting that citrullination of antithrombin may be involved in promoting carcinogenesis." (PMID 19183436, 2009). "Concurrently, the observed changes suggest that oxidative stress within the tumor was managed by antioxidant enzymes (SOD, CAT), as evidenced by the lack of variation in OSI compared to normal tissue." (PMID 40426975, 2025). "Overall, by constructing a closed catalytic cycle of GOx and CAT, the therapeutic efficiency of PDT would be no longer limited by the stress protein, nor the hypoxia environment in tumor, leading to a very strong inhibition of tumor growth." (PMID 39479443, 2024). "After observing no catalase monotherapy efficacy, we tested extracellular catalase in combination with radiation therapy (RT), a combination previously reported to be efficacious in CT26 and 4T1 tumor models." (PMID 37311396, 2023). "While RT improved survival in both models (P = 0.0005 for 4T1 and P = 0.0201 for CT26), the combination of CAT-ABP + alum and RT did not slow tumor growth or prolong survival compared to RT alone in either model." (PMID 37311396, 2023). "As in comparison to non-malignant cells, the tumor cells express less CAT, so the protective function of MAC of tumor cells is frequently ignored." (PMID 33477494, 2021). "Moreover, we observed a link between XO/CAT activity and inflammatory infiltration in the front and CAT activity in the centre of the tumour as well as between OSI and MDA and tumour budding, which may suggest the participation of oxidative stress in the remodelling of tumour stroma." (PMID 32575703, 2020). "It took into account that the outer membrane of tumor cells, in contrast to nonmalignant cells, is characterized by the expression of NOX1, catalase and SOD5,6,9,12,15,53,54." (PMID 31578342, 2019). "The present study aims at evaluating the activity of antioxidant enzymes, such as SOD (Cu/ZnSOD, and MnSOD), CAT, GPx, GR, and GST along with the concentration of MDA in tumor and adjacent noncancerous tissues of two histological types of NSCLC." (PMID 31781331, 2019). "Both molecular species are constantly generated by tumor cells, due to their active NOX1 and NOS, and are no longer decomposed at sites of catalase that has been inactivated by primary 1O2." (PMID 31558835, 2019). "Unexpectedly, the mean number of tumours per mouse in the group treated with PEG-CAT plus AFB1 resulted greater than that of the group treated with AFB1 alone, suggesting that catalase is not able to protect against AFB1-induced mouse lung tumorigenicity." (PMID 29794965, 2018). "To determine whether extratumoral H2O2 generates a field effect in vivo, we generated an admixed tumor xenograft containing three different cell types, namely, epithelial cells, CAFs and VybrantDiO-labeled FIBs, in the presence or absence of 500 U/ml extracellular catalase." (PMID 28102840, 2017). "EASA treatment resulted also in significant amelioration of tumor-induced oxidative stress by multiple mechanisms, involving modulation of lipid peroxidation, endogenous non-enzymatic (GSH) and enzymatic (SOD, CAT) antioxidant and detoxification systems." (PMID 27486371, 2015). "Recently, we demonstrated an important link between restoring catalase activity after chronic UVB exposures and decreasing tumor burden in male but not female mice." (PMID 23691100, 2013).